ENSG00000298116 (novel transcript)
Gene: Long non-coding RNA gene on chromosome 1 (161,528,409 to 161,530,931, reverse strand). Ensembl gene ENSG00000298116.
Gene Ontology:
Molecular function: triplet codon-amino acid adaptor activity
Biological process: translation